IFNGR1 (interferon gamma receptor 1)
Diseases named in the same sentence as IFNGR1 in open-access papers (continued):
Sharing a sentence is not in itself a finding about the gene and the disease.
tumor (continued). "The importance of the IFNγ pathway was confirmed by generating IFNγR1 KO glioblastoma cells which were more resistant to CAR T cell-mediated killing than wild-type tumor cells." (PMID 36189315, 2022). "In the context of co-cultures, tumor cell killing in the presence of SHP099 was considerably attenuated with IFNGR1 knockout OVCAR-8." (PMID 33446805, 2021). "Lack of signal transducer and activator of transcription 1 (STAT1), JAK1, or IFNGR1 in BRAFV600E/PTEN-/- mice increased tumor growth and decreased survival after anti-PD-1 treatment." (PMID 34827646, 2021). "In this study, we demonstrated the importance of IFNγ signaling in our tumor model by knocking out the IFNγ receptor, IFNGR1; we observed impaired T cell-mediated tumor killing as well as attenuated MHC class I expression in co-culture." (PMID 33446805, 2021). "After IFNGR1 deactivation, we evaluated the effect of this modification on tumor growth and anti-tumor immunity." (PMID 32155707, 2020). "To assess the anti-tumor activity of Prdm1−/−Trp1 Th-ctx cells, we transferred WT and Prdm1−/−Trp1 cells into irradiated WT or Ifngr1−/− B16-bearing recipients." (PMID 31924474, 2020). "Conversely, the expression of cytokine receptor-encoding genes IL7R, IFNGR1, IL18R1, and potentially IL23R (p = 0.065), was downregulated in HCC tumor-infiltrating MAIT cells." (PMID 32849590, 2020). "Experiments that activate IFNGR1 gene expression demonstrated strong activation of tumor-suppression signaling and sustained apoptosis." (PMID 33552133, 2020). "We observed similar results in CRPC, which showed decreased expression of the IFNGR1 gene in tumor samples with early relapse." (PMID 33552133, 2020). "On average, 30% of Blimp-deficient Trp1 cells still expressed GzmB, potentially explaining the tumor control observed in 50% of Ifngr1−/− recipients treated with Prdm1−/−Trp1 cells." (PMID 31924474, 2020). "To assess if combination therapy-improved mouse survival also depends on IL-7 and IFN-γ signalling in T cells, we followed long-term survival of CD45.1 tumour-bearing mice that were infused with WT, Ifngr1−/− or Il7r−/− total T cells." (PMID 27498556, 2016). "While combination therapy protected WT mice from MB49 tumour challenge, this protective effect was abolished in Ifngr1−/− mice." (PMID 27498556, 2016). "Since both Ifngr1−/− and Il7r−/− mice are incapable of eliminating primary tumours upon combination therapy, we contemplated memory cell expansion is defective in these KO mice." (PMID 27498556, 2016). "Combination therapy-improved survival of tumour-bearing mice that received WT total T cells but remained largely ineffective in those with adoptively transferred Il7r−/− or Ifngr1−/− total T cells." (PMID 27498556, 2016). "Gene expression profiling showed that the tumor microenvironment in Ifngr1−/−ApcMin/+ mice is highly inflammatory and is more permissive for tissue remodeling when compared to that in Ifngr1+/+ApcMin/+ mice." (PMID 27286456, 2016). "We next tested whether the mTORC1 inhibition could reverse the observed dysregulation of tumor glycolysis, chemokine expression, and IFNGR1 by RAC1A159V." (PMID 41160695, 2025). "Notably, tumors with IFNGR1KO treated with control IgG were significantly larger compared to IFNGR1WT treated with control IgG, suggesting a pleiotropic role of IFNGR1 in tumor growth." (PMID 41290625, 2025). "IFNG is upstream of STAT1 and activates its anti-tumor effects by binding to IFNGR1." (PMID 40659662, 2025). "Additionally, HKDC1 facilitates tumor immune escape by recruiting cytoplasmic STAT1 to IFNGR1, thereby revealing its critical role in the tumor immune microenvironment and providing theoretical support for combined immunotherapy." (PMID 40692442, 2025).
tumor (continued). "TPST2 modulates the tumor immune microenvironment via tyrosine sulfation of interferon gamma receptor 1 (IFNGR1) at residue Y397, attenuating STAT1 signaling, reducing HLA expression and antigen presentation, and consequently diminishing tumor-infiltrating lymphocytes." (PMID 41403951, 2025). "In summary, these results further support the hypothesis that IFNγ signaling can promote RMC tumor cell state changes, prompting further investigation into the pharmacological inhibition of myeloid-affiliated mediator, p300, which is downstream of IFNGR1." (PMID 41290625, 2025). "Furthermore, hyperactivated mTORC1 signaling shields RAC1A159V tumor from IFN-γ immune attack via down-regulating IFNGR1 expression due to increased glycosphingolipid biosynthesis." (PMID 41160695, 2025). "IFNGR1 gene expression was higher in the A5 than in E and T2 cell lines, indicating the effect of radiation and estrogen combined on IFNGR1 gene expression before tumor formation." (PMID 39765744, 2024). "Interestingly, however, the IFNGR1 signaling pathway in tumor cells has recently been shown to be essential for the efficacy of CTLA-4 and PD-1 ICB." (PMID 38982116, 2024). "Additionally, in CD16 monocytes, the remaining NPA genes, JAK3, PPIA, and TLR4 were up-regulated in tumor tissues, while IFNGR1 was down-regulated in tumor samples." (PMID 38149248, 2023). "Surprisingly, when we challenged IFNγR1−/− mice with wild-type tumors, we discovered that these mice could still largely control their tumors, suggesting that tumor sensing of IFNγ was now controlling tumor growth." (PMID 36881506, 2023). "Loss of IFNGR1 increased the growth of B7-H3 knockdown 105K cells in vivo, consistent with our prior data indicating that intact IFN-γ signaling is critical for the tumor-suppressive effects of B7-H3 inhibition." (PMID 36869048, 2023). "After validating that IFNγR1−/− B16Nectin1 cells were truly insensitive to IFNγ-mediated effects, we challenged wild-type mice with either control or IFNγR1−/− tumor cells, established palpable tumors, and began treatment with dual checkpoint blockade or IL-12 virotherapy." (PMID 36881506, 2023). "In addition, when we knocked out IFNGR1 in EMT6 tumor cells, cells retained their ability to form tumors in vivo, but the anti-tumor efficacy of the anti-PD-L1/TGFβ combination decreased." (PMID 37543621, 2023). "To test this hypothesis, we inhibited IFNγ signaling using an anti-IFNγR1 blocking antibody or enhanced IFNγ secretion with a human recombinant interleukin-12 (huIL12) in our extended in vitro co-culture tumor cell killing assay." (PMID 37550294, 2023). "Taken together, we propose a framework whereby STUB1 may confer ICB resistance by downregulating IFNGR1 on the cell surface, thus curbing the tumour cells’ ability to sense and respond to IFNγ." (PMID 35982220, 2022). "With regard to the mechanism that caused the infiltration of mature DCs, we demonstrated that loss of YTHDF1 in tumor cells could increase the expression of IFNGR1 in tumor cells." (PMID 35193930, 2022). "Genetic knockout of FAS or IFNGR1 in 5T4+ tumor cells abrogated tumor cell kill." (PMID 36271507, 2022). "Upregulation of IFNGR1 may thus activate JAK-STAT1 of tumor cells, which in turn facilitates effective immune surveillance." (PMID 35193930, 2022). "In agreement with previous studies, we found that Ifngr1 loss did not expedite tumor growth, probably because it eliminated downstream counteracting arms of IFN-γ signaling." (PMID 35230972, 2022). "Similarly, for the representative values of the expression levels of genes involved in tumor-T cell interaction, we selected six genes (IFNGR1, PD-L1, CXCL9, IFNγ, PD-1, and CXCR3) and termed this group as an immune response predictor (IRP)." (PMID 32795913, 2020). "Furthermore, more powerful fluorescence (P < 0.01), more metastatic foci (P < 0.01), and larger maximum metastatic tumor diameters (P < 0.01) were also detected in the IFNGR1 knockdown group." (PMID 29695839, 2018).
tumor (continued). "Tumor growth was also uncontrolled in mice bearing tumors with low IFNGR1 expression." (PMID 30135516, 2018). "However, when IFN-γ responsiveness was conferred on the tumor cells by introducing the IFNγR1 subunit, they became more immunogenic and were rejected through a T cell-dependent manner." (PMID 29780381, 2018). "However, there was a significant reduction of Ifngr1−/− or Il7r−/− T-cell infiltration into tumours, with the latter being more severe, which prevented further analysis of how IL-7Rα deficiency affects intratumoral T-cell effector function and Treg abundance." (PMID 27498556, 2016). "Additional analysis of tumour-infiltrating Ifngr1−/− T cells revealed a significantly higher proportion of Treg in CD4+ T cells, reduced ratios of CD4+ non-Treg/Treg and CD8+/Treg cells, and decreased CD4+IFN-γ+ TILs, as compared to tumour-infiltrating WT T cells." (PMID 27498556, 2016). "Therefore, the upregulation of IFNGR1 on tumor cells prompted us to further investigate whether this pathway mediates RMC tumor cell proliferation and hyperprogression in RMC in response to ICT." (PMID 41290625, 2025). "Consequently, IFNGR1 deficiency in MC38 tumor cells did not influence the efficacy of CD47-SIRPα ICB." (PMID 38982116, 2024). "In addition, loss of YTHDF1 mediated the overexpression of IFNGR1 and JAK1/2-STAT1 pathway in tumor cells, which might contribute to restored sensitivity to antitumor immune response." (PMID 35193930, 2022). "They revealed that the loss of the tumor suppressive transcription factor Elf5, together with its ubiquitin ligase FBXW7, could activate intrinsic IFN-γ signaling and promote tumor progression and metastasis, all through the stabilization of IFNGR1 at the protein level." (PMID 33005420, 2020). "Immune and Inflammatory Modulation: IFNGR1 and PTGS2 (COX-2) play roles in immune responses and inflammation, which can contribute to a tumor-supportive microenvironment." (PMID 41303451, 2025). "To further validate the critical role of Pik3 cd and Ifngr1 in the anti‐tumor immune effects of FAST therapy, we carried out the inhibition of PI3Kδ in leukocytes and IFNγR in tumor cells." (PMID 40135850, 2025). "IFNGR1/2 and IFNAR1, serving as the receptor for IFN-γ and IFN-α respectively, are critical in cancer cell fate and tumor microenvironment." (PMID 40708945, 2025). "IFNG and IFNGR1 are upstream regulators of STAT1, and the binding of IFNG to IFNGR1 activates STAT1, exerting anti-tumor effects." (PMID 40659662, 2025). "To assess the direct impact of IFNGR1 in RMC tumor cells, we used CRISPR gene editing to genetically knockout IFNGR1 in MSRT1 mouse cell lines." (PMID 41290625, 2025). "We stained the IFN-γ and TNF-α receptors on the tumor cells and flow cytometry revealed that the PI9 overexpressing cell lines express IFNGR1 and TNFAR1 receptors at lower frequencies than the parental tumor cells." (PMID 38307835, 2024). "Tumor cells that were treated with EZH2 inhibitor alone or in combination with anti-PD1 had increased H2-K1, B2m, and Ifngr1 expression, and decreased expression of neutrophil-recruiting chemokines such as Cxcl3, Cxcl5, and Ppbp (a.k.a Cxcl7)." (PMID 38265267, 2024). "To further examine the impact of IFN-γ signaling in tumor cells, we used CRISPR-Cas9 to knockout the interferon gamma receptor 1 (IFNGR1) in B7-H3 knockdown 105K cells." (PMID 36869048, 2023). "It has been reported that, when EZH2 was knocked down in PCa, IFNGR1 expression was restored, and when IFN therapy was applied, significant activation of IFN-JAK-STAT1 tumor suppressor signaling occurred." (PMID 36358967, 2022). "In contrast, RPM scores were positively correlated with IFNGR1, TGF-β, and TNF-α families, which play pro-tumor roles in TIME." (PMID 35493519, 2022).
tumor (continued). "Further, a consensus on the role of tumor expression of IFNAR1 and IFNGR1 regarding RT response still cannot be reached, as either an essential role or a dispensable role was reported." (PMID 34830176, 2021). "Furthermore, an early study showed that IFN-γ induced tumor dormancy when IFNGR1 expression level was low, but resulted in tumor elimination when it was high, indicating that the absolute expression level of IFNGR1 or signaling strength could determine the final outcomes of IFN-γ signaling." (PMID 34830176, 2021). "For instance, IFN-γ signaling is known as an essential effector molecule for anti-tumor immune response, which must bind the IFN-γ receptor (IFNGR1 or IFNGR2) to modulate the JAK–STAT pathways and affects the immune cell activation." (PMID 34124058, 2021). "IFNγ receptor (Ifngr1) expression was required on host cells, not tumor cells, for CD40 agonist-mediated tumor control." (PMID 41676732, 2026). "IFN-γ triggers the transcription of key anti-tumour genes, including major histocompatibility complex class I, FAS, CASPASE-1, and growth-inhibitory genes, via IFNGR1-mediated JAK-STAT signalling, thereby enhancing immune cell activation and tumour cell apoptosis." (PMID 40657375, 2025). "We also observed that tumor cells that engaged senescence-related transcriptional programs, or “Sen-High” cells, upregulated IFN-γ signaling machinery, including Ifngr1, Ifngr2, Jak1, Jak2, Irf1, and Stat1, as well as IFN-γ target genes Cxcl9, Cxcl10, and Tap1." (PMID 40299790, 2025). "Increased expression of Ifngr1, Ifngr2 and Ifnar2 in cluster 0 of the CAR-T-treated group (compared to mock-T-treated), indicates this could be a tumor adaptive mechanism to Ifn-γ and Ifn-α signaling mediated by CAR-T cell therapy." (PMID 40568084, 2025). "In parallel, RMC tumor cells upregulated expression of IFNGR1, which normally engages IFNγ to activate proliferation of myeloid lineage immune cells via the MAPK signaling pathway as part of the innate immune response." (PMID 41290625, 2025). "Moreover, IFIT1 cytoplasmic expression was significantly down-regulated by KPT-9274, suggesting that KPT-9274 downregulates Wnt/β-Catenin pathway via a suppression of IFNGR1 and IFIT1, contributing to the anti-tumor effects." (PMID 38424218, 2024). "Importantly, we found the T cell cluster (cluster 13) was the major source of IFN-γ within the tumor microenvironment, while the IFN-γ receptor (IFNGR1) was expressed in each of the clusters." (PMID 39388288, 2024). "To understand whether IFNγ sensing by CD8 T cells directly affected the efficacy of anti-tumor responses, we used a mouse model whereby IFNγ sensing was ablated in CD8 T cells by deleting IFNγR1 specifically in mature CD8 T cells (CD8-IFNγRKO)." (PMID 36658158, 2023). "IFNγ receptor genes IFNGR1, IFNGR2 and the downstream effector IRF1 have been reported to be expressed on a PNET cell line QGP-1, and IFNγ treatment could inhibit tumor growth and induce apoptosis in vitro, indicating a direct anti-PNET effect of IFNγ." (PMID 38020179, 2023). "This suggests that DuoBody-CD3x5T4–mediated cross-linking of T cells and tumor cells still results in efficient T-cell activation but that the tumor cells lacking IFNGR1 have become less sensitive to T cell–mediated kill in a Fas-independent manner." (PMID 36271507, 2022). "Loss of YTHDF1 mediated overexpression of interferon (IFN)-γ receptor 1 (IFNGR1) and JAK/STAT1 signaling pathway in tumor cells, which might contribute to restored sensitivity to anti-tumor immunity." (PMID 35193930, 2022). "First, while essential roles of host IFNs signaling in dictating RT have been established, the actual role of tumor expression of IFNAR1 and IFNGR1 may depend on the dose/fraction of RT used and the specific tumor types." (PMID 34830176, 2021). "Additionally, IHC staining of tissues from tumor-bearing mice revealed IFNGR1 expression only in the PC3 group, and IFNGR1 was activated only by IFN-γ in this group." (PMID 33692219, 2021).
tumor (continued). "The expression of CTGF and MYB was significantly higher in HCC tissues than that in the adjacent non-tumor tissues (p < 0.05), while the expression of BCLAF1, IFNGR1, and HIVEP2 was significantly lower in HCC tissues than in adjacent non-tumor tissues (p < 0.05)." (PMID 34616668, 2021). "IFNGR1 deactivation influenced the effect of certain immune cells on tumor development, particularly on TC-1 versus TC-1/dIfngr1 tumors, where IFNGR1 deactivation eliminated the anti-tumor effect of CD8+ cells and pro-tumor effect of macrophages." (PMID 32155707, 2020). "Combined immunotherapy with PD-L1 blockade and DNA vaccination showed that IFNGR1 deactivation did not reduce tumor sensitivity to anti-PD-L1." (PMID 32155707, 2020). "To this end, we analyzed TCM cells in the spleen of Il7r−/− and Ifngr1−/− tumour-bearing mice treated with or without combination therapy." (PMID 27498556, 2016). "Our results suggest that p300 engagement and subsequent myeloid mimicry occur via the binding of IFNγ to the IFNGR1 that is overexpressed in RMC tumor cells after ICT, representing a non-canonical downstream pathway of interferon gamma signaling that promotes lineage plasticity." (PMID 41290625, 2025). "Particularly noteworthy, the increase in interaction pairs involving IFNG_(IFNGR1+IFNGR2) in OT samples, indicating that the combination therapy enhances the secretion of interferon by CD8+ T cells, which in turn interact with malignant cells to execute anti‐tumour effect." (PMID 39415331, 2024). "The Interferon-Gamma Receptor 1 (IFNGR1) gene affects the development and metastasis of solid cancers as demonstrated in murine mammary carcinoma 4T1 after being implanted into the mammary fat pads of IFN-gamma(−/−) mice, where the tumor developed and metastasized considerably rapidly." (PMID 39765744, 2024). "On the other hand, IFNGR1 gene expression was not significantly different between normal tissues and tumors, indicating that the IFNs could act before tumor formation." (PMID 39765744, 2024). "To mimic IFN conditions in the tumor microenvironment (TME), we added IFNγ exogenously in SCC cells since (i) IFNγ pathway is the most significant pathway negatively regulated by TP63, (ii) IFNγ receptors (IFNGR1, IFNGR2) have higher expression than IFNα receptors (IFNAR1, IFNAR2) in SCC cells." (PMID 38509096, 2024). "Importantly, loss of STUB1, but not PTPN2, increased the surface expression level of IFNGR1 in all three tumour lines, a result highly consistent with B16-F10 cells." (PMID 35982220, 2022). "In tumors, IFNGR1 deactivation did not lead to PD-L1 or MHC-I reduction on tumor cells." (PMID 32155707, 2020). "We observed that only the ApcMin allele, but not the wild-type allele, was detected in tumors arising from Ifngr1−/−ApcMin/+ mice, as in those from ApcMin/+ mice, suggesting that lack of IFN-γ receptor led to increased tumor multiplicity similarly via loss of the wild-type Apc allele." (PMID 27286456, 2016). "Some of these considerations also may help to explain previous reports in which tumor cells expressing a dominate negative IFNγR1 exhibited increased tumor growth, as this dominate negative receptor can still bind IFN-γ and perhaps sequester it from other cells within the tumor." (PMID 32001684, 2020). "In the context of the PS organelle, NONO can sequester the interferon-gamma receptor 1 (IFNGR1) mRNA in HCC cancer cells, promoting tumor cells escape from immunosurveillance by T-cells." (PMID 38493226, 2024). "High expression levels of AKT1 (p = 0.01), IFNGR1 (p = 0.01), and BRCA2 (p = 0.02) were predictive of early trabectedin treatment failure, irrespective of tumor grade." (PMID 35267598, 2022). "Next, to determine how responsiveness to IFNγ affects tumor growth and response to checkpoint inhibitors, Ifngr1 was silenced in CMT167 cells using two separate shRNAs against murine Ifngr1 and a nontargeting control vector." (PMID 31133614, 2019).